ALK (ALK receptor tyrosine kinase)
Diseases named in the same sentence as ALK in open-access papers (continued):
Sharing a sentence is not in itself a finding about the gene and the disease.
metastatic prostate carcinoma (2 papers, 2019 to 2022). A carcinoma that arises from the prostate gland and has spread to other anatomic sites. "ALK expression in metastatic prostate cancers was associated with distinct transcriptional changes." (PMID 36337169, 2022). "In metastatic prostate cancer, we observed that ALK expression is a relatively common feature of NEPC." (PMID 36337169, 2022). "Here, we aim to delineate the role of ALK genomic and expression changes in primary and metastatic prostate cancer." (PMID 36337169, 2022). "We observed ALK protein expression in 5 of 52 (9%) of metastatic prostate cancer cases, of which 4 of 5 had neuroendocrine features." (PMID 36337169, 2022). "To study ALK protein expression in advanced metastatic prostate cancer, we performed ALK IHC on 52 cases of the UW rapid autopsy cohort." (PMID 36337169, 2022). "Here we assessed the spectrum of ALK alterations in localized and advanced metastatic prostate cancer." (PMID 36337169, 2022). "Here we comprehensively investigate the expression of ALK in localized and advanced metastatic prostate cancer." (PMID 36337169, 2022).
mucinous lung adenocarcinoma (2 papers, 2021 to 2025). "The most significant independent prognostic factors of ALK positivity were age, solid-predominant-subtype tumours, mucinous lung adenocarcinoma, solid tumours and no air bronchograms on CT." (PMID 33707479, 2021).
mucosal melanoma (2 papers, 2021). A melanoma that arises from a mucosal site. "Anaplastic lymphoma kinase (ALK) fusions have been described in mucosal melanoma, specifically the EML4-ALK fusion and an alternate ALK isoform, ALK-AT1." (PMID 35008570, 2021).
myeloproliferative disorder (2 papers, 2012 to 2026). A clonal hematopoietic stem cell disorder, characterized by proliferation in the bone marrow of one or more of the myeloid (i.e., granulocytic, erythroid, megakaryocytic, and mast cell) lineages. "The lymphoma associated oncogene NPM/ALK significantly altered the expression of 91phosphopeptides whilst the myeloproliferative disorder oncogenes BCR/ABL, TEL/PDGFRβ, Kit D816V, and Fip1L/PDGFRα changed the expression of 94, 114, 111 and 68 respectively." (PMID 22745689, 2012).
myoepithelial carcinoma (2 papers, 2021 to 2022). "Some cases involved incorrect histogenesis of the tumour (such as ALK negative ALCL misdiagnosed as myoepithelial carcinoma)." (PMID 36200017, 2022).
plasma cell neoplasm (2 papers, 2021 to 2024). A clonal proliferation of immunoglobulin-secreting plasma cells. "Chemotherapy regimens for plasma-cell tumors, such as proteasome inhibitors and immunomodulators, may be effective against ALK+ LBCL." (PMID 39906668, 2024). "Our case highlights that a small percentage of patients with plasma cell neoplasms carries ALK fusion and may benefit from ALK inhibition." (PMID 33731690, 2021).
pneumonia (2 papers, 2018 to 2023). An acute, acute and chronic, or chronic inflammation focally or diffusely affecting the lung parenchyma, caused by an infection in one or both of the lungs (by bacteria, viruses, fungi, or mycoplasma.). "Therefore, we suggest that although the incidence of ALK inhibition-associated pneumonia is low, clinicians should still be sufficiently vigilant." (PMID 37287014, 2023). "The expression levels of ALK fusion genes in healthy controls and patients with pneumonia were 0.34 to 8.37 (mean 3.72) and 0.41 to 8.35 (mean 3.72) respectively." (PMID 29587818, 2018). "However, several case studies still report that ALK inhibitors combined with chest radiotherapy significantly increase the incidence of pneumonia." (PMID 37287014, 2023). "Statistical analysis showed that expression of the ALK fusion gene is significantly higher in the plasma of patients who were ALK fusion gene (+) than those who were fusion gene (−), and also higher than expression in the healthy and pneumonia patients (P < 0.01)." (PMID 29587818, 2018).
psoriasis (2 papers, 2013 to 2025). An autoimmune condition characterized by red, well-delineated plaques with silvery scales that are usually on the extensor surfaces and scalp. "There was a significantly higher expression of ALK in BCC compared to normal skin, psoriasis, and SCC (p<0.05)." (PMID 24163262, 2013).
pulmonary embolism (2 papers, 2020 to 2022). The obstruction of the pulmonary artery or one of its branches by an embolus, sometimes associated with infarction of the lung. "The positive results of ALK and PD-L1 genomic alterations may indicate an increased risk of pulmonary embolism in patients with NSCLC." (PMID 32677947, 2020). "For example, the first‐line PROFILE 1014 phase III trial conducted in ALK‐rearranged NSCLC showed that the rate of grade 3 or 4 pulmonary embolism was 8% for the crizotinib arm and 7% for the chemotherapy arm." (PMID 35510711, 2022).
pulmonary TB (2 papers, 2017 to 2025). "In our review of the literature, we found only one case of coexisting ALK+ ALCL and pulmonary TB." (PMID 28490385, 2017). "Here, we report a rare case of a rapidly growing ALK‐negative, neurotrophic tyrosine receptor kinase 3 (NTRK3)‐positive pulmonary IMT in a 46‐year‐old man with a history of pulmonary tuberculosis." (PMID 41368177, 2025).
Sinus bradycardia (2 papers, 2017 to 2023). Bradycardia related to a mean resting sinus rate of less than 50 beats per minute. "Sinus bradycardia is frequently observed in patients treated with crizotinib, a receptor tyrosine kinase inhibitor used for the treatment of anaplastic lymphoma kinase (ALK)-rearranged non-small cell lung cancer (NSCLC)." (PMID 28217366, 2017). "With the widespread use of alectinib in patients with anaplastic lymphoma kinase (ALK)‐positive non‐small‐cell lung cancer (NSCLC), its cardiotoxicity has gradually emerged, including new‐onset sinus bradycardia (SB)." (PMID 36535917, 2023).
spindle cell sarcoma (2 papers, 2020 to 2025). A malignant mesenchymal neoplasm composed of spindle-shaped cells. "The diagnosis of ALK-negative IMTs is challenging as their morphology is strikingly similar to the spindle cell sarcoma with myofibroblastic characteristics, including their inflammatory features." (PMID 32195970, 2020).
spitzoid melanoma (2 papers, 2022 to 2025). "Spitzoid melanomas often necessitate a panel of melanocytic and proliferation markers, with molecular testing (e.g., for Harvey rat sarcoma viral oncogene homolog (HRAS) mutations or anaplastic lymphoma kinase (ALK) fusions) playing a confirmatory role." (PMID 40984902, 2025).
thalassemia (2 papers, 2016 to 2022). An inherited blood disorder characterized by a decreased synthesis of one of the polypeptide chains that form hemoglobin. "Moreover, mutations affecting both the α-thalassemia/mental retardation syndrome X-linked (ATRX) gene or anaplastic lymphoma receptor tyrosine kinase (ALK) are also common in NB." (PMID 35687185, 2022).
thymic carcinoma (2 papers, 2017 to 2022). Thymic carcinoma (TC) is a type of thymic epithelial neoplasm characterized by a high malignant potential. "The receptor tyrosine kinases ALK and ERBB4, the serine/threonine kinase ATM, and the GTPase NRAS were mutated in one thymic carcinoma each." (PMID 27844328, 2017). "Motivated by the two thymic carcinomas with an FGFR3 mutation and the one carcinoma with an ALK mutation, we also performed FISH for these two genes." (PMID 27844328, 2017).
Acute hepatitis (1 paper, 2021). Acute hepatic injury resulting from inflammation typically accompanied by increased serum alanine transaminase activity. "Herein, we report a real-world case of acute hepatitis induced by crizotinib in an ALK-rearranged positive NSCLC patient, in whom the treatment shift for a second-generation ALK-inhibitor after the event recovery." (PMID 33509141, 2021). "Herein, we report a case of acute hepatitis induced by crizotinib in a 32-years-old female diagnosed with metastatic NSCLC, harboring the ALK-rearrangement." (PMID 33509141, 2021).
adenopathy (1 paper, 2020). "The ALK+ ALCL form presents more frequently during childhood as an advanced stage disease with adenopathy and BM infiltration, whereas ALK− ALCL is an adult disease, mostly diagnosed in 40 years old adults." (PMID 32375354, 2020).
adrenal neoplasms (1 paper, 2026). "Therefore, we advocate for the inclusion of this entity in the differential diagnosis of adrenal neoplasms and recommend routine ALK testing in similar challenging cases to guide precise management and avoid therapeutic errors." (PMID 41695335, 2026).
adrenal neuroblastoma (1 paper, 2022). "ALK mutations are enriched in thoracic compared to adrenal neuroblastoma, which may be caused by stronger dependency of neuroblasts on ALK signaling, in line with higher ALK expression in mouse and human neuroblasts compared to chromaffin cells." (PMID 35681734, 2022).
adrenal pheochromocytoma (1 paper, 2016). "In parallel we examined the activity of PF-06463922 in conjunction with gain-of-function ALK variants expressed in PC12 cells, which is a clonal rat adrenal pheochromocytoma cell line with enteric cell origin, with the ability to differentiate and extend neurites upon protracted ERK1/2 stimulation." (PMID 27483357, 2016).
Airway obstruction (1 paper, 2025). Obstruction of conducting airways of the lung. "Notably, observational studies suggest that COPD is independently associated with reduced rates of EGFR mutations and ALK rearrangements, with mutation frequency inversely correlated to airway obstruction severity." (PMID 40507634, 2025).
Allergy (1 paper, 2015). An allergy is an immune response or reaction to substances that are usually not harmful. "This is a randomized, double-blind, single-centre, placebo controlled, two arm time course study based in the United Kingdom comparing sublingual allergy immunotherapy tablet (GRAZAX®, ALK-Abello Horsholm, Denmark) plus standard treatment with placebo plus standard treatment." (PMID 26682038, 2015).
alpha thalassemia/mental retardation syndrome (1 paper, 2019). "More recent research points to somatic mutations in genes such as anaplastic lymphoma kinase (ALK), phosphatase and tension homolog (PTEN) or alpha thalassemia/mental retardation syndrome X-linked (ATRX), among others." (PMID 31861671, 2019).
ameloblastoma (1 paper, 2025). The most common odontogenic tumor, arising from the epithelial component of the embryonic tooth and usually affecting the molar-ramus region of the mandible or maxilla. "Additional studies showed gene expression profile differences between plexiform and follicular ameloblastomas, with follicular ameloblastomas expressing variants of BRAF, KMT2D, and ABL1, while plexiform ameloblastomas expressed variants of ALK, BRAF, KRAS, KMT2D, SMO, KMT2A, and BRCA2." (PMID 38607614, 2025).
amyotrophic lateral sclerosis (1 paper, 2021). Amyotrophic lateral sclerosis (ALS) is a neurodegenerative disease characterized by progressive muscular paralysis reflecting degeneration of motor neurons in the primary motor cortex, corticospinal tracts, brainstem and spinal cord. "Another genome-wide association analysis study showed that ALK SNP is one of the top-ranked SNPs significantly associated with sporadic amyotrophic lateral sclerosis (ALS)." (PMID 33452442, 2021).
Anorexia (1 paper, 2023). Lack of desire to eat (loss of appetite). "Here, we investigated the expression of ALK and the downstream intracellular pathways in female rats subjected to the activity-based anorexia (ABA) model, which reproduces important features of human AN." (PMID 37432348, 2023).
Ataxia (1 paper, 2011). Ataxia refers to impaired coordination of voluntary muscle movement. "In humans, SNPs in ALK are associated with resistance to ethanol-induced ataxia as measured by body sway in response to an alcohol challenge." (PMID 21799923, 2011).
atherosclerosis (1 paper, 2020). A disease characterized by the build-up of fatty material and calcium deposition in the arterial wall resulting in partial or complete occlusion of the arterial lumen. "Binding TGF-β to the receptor complex triggers activation of type I receptor terms as ALK, which can initiate downstream signaling including Smad phosphorylation, MAPK and PI3K-Akt signaling, while all three cascades have been implicated in the development of atherosclerosis." (PMID 32065217, 2020).
autism (1 paper, 2017). Persistent deficits in social interaction and communication and interaction as well as a markedly restricted repertoire of activity and interest as well as repetitive patterns of behavior. "These two regions are located in the intron region of two distinct genes, anaplastic lymphoma receptor tyrosine kinase (ALK), and autism susceptibility candidate 2 (AUTS2)." (PMID 28203233, 2017).
Autoimmunity (1 paper, 2024). The occurrence of an immune reaction against the organism's own cells or tissues. "Although its etiology and pathogenesis are still controversial, the development of IMT has been hypothesized to be affected by many causes, such as infection, trauma, surgery, autoimmunity, and chromosomal variation of the ALK gene." (PMID 38485843, 2024).
bone sarcoma (1 paper, 2023). A sarcoma that arises from the bone. "Furthermore, we discovered two GAs in the ALK and BRAF genes that occurred in bone sarcomas, while three GAs in the EGFR gene and one GA in the ERBB2 gene were only found in STS." (PMID 37546405, 2023).
brain cancer (1 paper, 2021). A primary or metastatic malignant neoplasm affecting the brain. "LDK378 is a recently developed ALK inhibitor that is highly permeable to the BBB and used in the treatment of brain cancer." (PMID 33452442, 2021).
bronchogenic lung cancer (1 paper, 2023). "A patient with primary bronchogenic lung cancer (stage IV of left upper central type high to moderately differentiated adenocarcinoma) was treated with crizotinib when the ALK gene deletion mutation was shown." (PMID 37276214, 2023).
cardiac conduction disease (1 paper, 2024). "Results from another previous pharmacovigilance analysis also revealed that ALK and ROS1 inhibitors induced higher odds of cardiac conduction disease than other targeted therapies." (PMID 38357305, 2024).
cardiac hypertrophy (1 paper, 2025). "Moreover, an older study in mice reports cardiac hypertrophy, low blood pressure, and increased heart rate upon ubiquitous expression of a constitutively active form of the LTK receptor that shares a high degree of structural and functional conservation with its closest relative ALK." (PMID 40382638, 2025).
cardiotoxicity (1 paper, 2022). Toxicity that impairs or damages the heart. "We also studied the onset time and the fatality proportion, which showed ALK-TKI-associated cardiotoxicity may have the earlier time of onset and higher fatality proportion." (PMID 35370632, 2022).
celiac disease (1 paper, 2016). An autoimmune genetic disorder with an unknown pattern of inheritance that primarily affects the digestive tract. "Its association with celiac disease or villous atrophy further distinguishes itself with ALK positive ALCL." (PMID 27612448, 2016).
central nervous system anaplastic large cell lymphoma (1 paper, 2025). An anaplastic large cell lymphoma that affects the brain, meninges, or spinal cord. "This case represents the first globally successful instance of treating ALK-negative primary central nervous system anaplastic large-cell lymphoma (PCNSALCL) with CAR-T therapy." (PMID 40777017, 2025).
cervical intraepithelial neoplasia (1 paper, 2025). "This study evaluated the diagnostic value of ALK, RPS14 genes, and key components of the PI3K/Akt/NF - κ B pathway for high-grade cervical intraepithelial neoplasia (HSIL) through ROC curve analysis." (PMID 40978038, 2025).
cholestasis (1 paper, 2022). Impairment of the bile flow caused by obstruction within the liver, or outside the liver in the bile duct system. "Single and double vaccination did not increase parameters reflecting the cytolysis of hepatocytes (ALT and AST) compared to the control but led to 1.4–1.9-fold increase in the parameter reflecting the cholestasis (ALK), especially during boosted treatment." (PMID 36432733, 2022).
clear cell kidney carcinoma (1 paper, 2016). "FN1 (15th by MUFFINN yet below 8000th by the gene-centric methods in clear cell kidney carcinoma (KIRC) samples) is a novel fusion partner of ALK in myofibroblastic tumors." (PMID 27333808, 2016).
colitis (1 paper, 2025). Inflammation of the colon. "Based on these findings, infectious diarrhea and intestinal tumors were ruled out, confirming a diagnosis of intestinal ulceration and colitis linked to ALK inhibitors, classified as a CTCAE grade 3 adverse event." (PMID 40114680, 2025). "Currently, there is no established pharmacological treatment for ALK inhibitor-associated intestinal ulcers and colitis due to the rarity of this condition." (PMID 40114680, 2025). "It remains uncertain whether switching to another ALK inhibitor will lead to a recurrence of intestinal ulcers and colitis." (PMID 40114680, 2025). "The mechanism by which ALK inhibitors induce intestinal ulceration and colitis remains unclear." (PMID 40114680, 2025).
corneal ulcer (1 paper, 2024). Area of epithelial tissue loss from corneal surface; associated with inflammatory cells in the cornea and anterior chamber. "There are scarce data on ALK presenting interface keratitis, as the presence of sutures predisposes to “typical” corneal ulcer- localized in corneal stroma." (PMID 38673599, 2024).
cyst (1 paper, 2020). A sac-like closed membranous structure that may be empty or contain fluid or amorphous material. "Tumor cells proliferating around the cyst wall were anaplastic lymphoma kinase (ALK) (+), pan-tropomyosin receptor kinase (−), smooth muscle actin (SMA) (−), transducer-like enhancer of split 1 (−), BCL6 corepressor gene (−), and alpha-internexin (−), using immunohistochemistry." (PMID 32448976, 2020).
Dermatofibroma (1 paper, 2025). "Dermatofibroma typically exhibits Factor XIIIa positivity but lacks ALK expression." (PMID 40688914, 2025).
diffuse astrocytoma (1 paper, 2023). A low-grade (WHO grade II) astrocytic neoplasm. "These include diffuse astrocytoma, MYB- or MYBL1-altered; diffuse low-grade glioma, MAPK pathway-altered; polymorphous low-grade neuroepithelial tumor of the young (BRAF mutations and FGFR2 fusions); and infant-type hemispheric glioma (alterations in NTRK, ROS1, ALK, or MET)." (PMID 37509316, 2023).
electrolyte disorders (1 paper, 2025). "Anaplastic lymphoma kinase(ALK) inhibitors have been linked to the development of peripheral edema and, in rare cases, electrolyte disorders and kidney failure." (PMID 40911105, 2025).
embryonal carcinoma (1 paper, 2021). A non-seminomatous malignant germ cell tumor characterized by the presence of large germ cells with abundant cytoplasm resembling epithelial cells, geographic necrosis, high mitotic activity, and pseudoglandular and pseudopapillary structures formation. "However, embryonal carcinoma with a predominant solid pattern can mimic ALK- ALCL." (PMID 34572893, 2021).
Encephalopathy (1 paper, 2014). Encephalopathy is a term that means brain disease, damage, or malfunction. "A syndromic presentation associating congenital neuroblastoma with severe encephalopathy and an abnormal shape of the brainstem has been described in patients harbouring de novo germline F1174V and F1245V ALK mutations." (PMID 24811761, 2014).
endophthalmitis (1 paper, 2020). An infectious process affecting the internal structures of the eye. "The most frequently reported adverse reactions after PKP/ALK were primary GF (n = 13; 0.022%) followed by infectious keratitis (n = 7, 0.012%) and endophthalmitis (n = 6, 0.01%)." (PMID 32308948, 2020).